SGK1 (serum/glucocorticoid regulated kinase 1)
Diseases named in the same sentence as SGK1 in open-access papers (continued):
Sharing a sentence is not in itself a finding about the gene and the disease.
pulmonary fibrosis (6 papers, 2008 to 2025). Chronic progressive interstitial lung disorder characterized by the replacement of the lung tissue by connective tissue, leading to progressive dyspnea, respiratory failure, or right heart failure. "Our findings provide a rationale for the discovery of novel therapeutic approaches by targeting SGK1 to ameliorate profibrotic macrophage activation in lung fibrosis." (PMID 38250161, 2024). "IHC staining further showed that SGK1 expression was significantly increased in the lungs of different pulmonary fibrosis patients compared with healthy controls." (PMID 38250161, 2024). "In the current study, we demonstrated that SGK1 was drastically elevated both in the lungs of pulmonary fibrosis patients and IPF mouse model, and was strongly correlated with disease severity." (PMID 38250161, 2024). "Firstly, SGK1 was highly increased either in the lung of patients with pulmonary fibrosis and mouse models and was positively correlated with histological characteristics of this disease." (PMID 38250161, 2024). "Our study further enriched the role of SGK1 in fibrosis, and solidly supported the potential therapeutic value of SGK1 inhibition in pulmonary fibrosis." (PMID 37345264, 2023). "Clearance of senescent cells following treatment with ABT263 or SGK1‐ specific inhibitor EMD638683 ameliorated HFD‐induced pulmonary fibrosis and reduced SASP." (PMID 37345264, 2023). "Overexpression of SGK1 has been observed in various fibrotic diseases, including pulmonary fibrosis, diabetic renal fibrosis, liver cirrhosis, hypertensive cardiac fibrosis, peritoneal fibrosis, and Crohn’s disease." (PMID 35222400, 2022). "In addition, the inhibition of SGK1 by EMD638683 was found to alleviate high-fat diet-induced pulmonary fibrosis and activation of the integrin-inflammasome pathway." (PMID 38250161, 2024). "Considering the important role of macrophages played in pulmonary fibrosis 25, we further explored whether the high expression of SGK1 was related to any phenotype changes of macrophage." (PMID 38250161, 2024). "Since p16 exacerbated HFD‐induced pulmonary fibrosis via the regulation of SGK1, we next asked whether inhibition of SGK1 could rescue this process." (PMID 37345264, 2023). "Furthermore, based on the specific regulatory signalling pathways identified here, we demonstrated that clearance of senescent cells by administration of ABT263 or the SGK1‐specific inhibitor EMD638683 ameliorated HFD‐induced pulmonary fibrosis." (PMID 37345264, 2023). "Although there is insufficient evidence to support that SGK1 may also be involved in epigenetic regulation process, the regulation of pulmonary fibrosis-related gene expression at the transcriptional level through chromatin and histone modification has attracted more attention." (PMID 38250161, 2024). "At the same time, the acetylation of H3K27 may promote gene transcription thus increase the expression and activation of SGK1 to form a positive feedback loop 38, which could further explain the progressive exacerbation of pulmonary fibrosis after BLM + LPS administration." (PMID 38250161, 2024). "SGK1 activated the integrin‐inflammasome pathway, while cellular glycolysis induced SASP and aggravated the accumulation of senescent cells and pulmonary fibrosis." (PMID 37345264, 2023). "Therefore, we hypothesized that p16 regulated HFD‐induced lung fibrosis via SGK1." (PMID 37345264, 2023). "P16‐mediated SGK1 accumulation promoted activation of the integrin‐inflammasome pathway and cellular glycolysis, increased secretion of SASP and aggravated accumulation of senescent cells and pulmonary fibrosis." (PMID 37345264, 2023). "Interestingly, this study revealed the critical role of SGK1 in p16‐ positive senescent cells, thus, exacerbating HFD‐induced pulmonary fibrosis." (PMID 37345264, 2023).
triple-negative breast carcinoma (6 papers, 2009 to 2025). An invasive breast carcinoma which is negative for expression of estrogen receptor (ER), progesterone receptor (PR), and human epidermal growth factor receptor 2 (HER2). "However, recently it was shown that dihydrotestosterone abolished Sgk1 increases caused by dexamethasone stimulation in triple-negative breast cancer cells." (PMID 38303978, 2023). "Because the PI3-K/SGK1 pathway represents an alternative to ER-, PR- and Her2-mediated growth signaling, increased SGK1 expression could contribute to susceptibility to triple negative breast cancers." (PMID 19461886, 2009). "Natural compounds (e.g., Salvia miltiorrhiza-derived exosomes) inhibit SGK1-FOXO3a signaling, inducing autophagy/apoptosis in triple-negative breast cancer (preclinical)." (PMID 40917754, 2025). "Accordingly, we find that Src positively regulates SGK1 expression in triple negative breast cancer cells, which exhibit a prominent signalling network governed by Src family kinases." (PMID 30655532, 2019).
asthma (5 papers, 2016 to 2025). "While Sgk1 has been implicated as an important factor in driving T cell polarity in murine models, very little is known about its role in humans and asthma." (PMID 36611927, 2022). "Furthermore, we identified a miRNA previously reported to be associated with asthma pathogenesis, miR-19a, that was bioinformatically predicted to bind SGK1." (PMID 36611927, 2022). "Although SGK1 was found to be upregulated in individuals with asthma, SGK1 and miR-19a in CD4+ T cells appear to have a common regulatory relationship, independent of the disease." (PMID 36611927, 2022). "Using a gene array, we found the serum/glucocorticoid-regulated kinase 1 (SGK1) gene to be upregulated in circulating peripheral blood mononuclear cells (PBMCs) from individuals with asthma." (PMID 36611927, 2022). "Utilizing a focused gene array, we identified the serum/glucocorticoid-regulated kinase 1 (SGK1) gene to be upregulated in circulating peripheral blood mononuclear cells, which included T cells, from individuals with asthma." (PMID 36611927, 2022). "Dickkopf-1 has been demonstrated to regulate Th2 cell effector functions via the mechanistic target of rapamycin (mTOR) pathway and SGK-1, with implications for Leishmania major (L. major) infection and house dust mite-induced asthma." (PMID 34572015, 2021). "Additionally, HBT has been shown to inhibit asthma development by blocking the SGK-1/NF-κB signaling pathway." (PMID 41011177, 2025). "Like previous studies, our findings suggest a role for SGK1 in asthma." (PMID 36611927, 2022). "Our demonstration of the position of SGK1 at the axis of T cell differentiation may indicate its role in the pathogenesis of multiple asthma phenotypes." (PMID 36611927, 2022). "Thus, further studies examining SGK1 and miR-19a are warranted to determine their precise role in T cell polarization and the development of asthma in humans." (PMID 36611927, 2022). "Our findings suggest a role for SGK1 as a potential future target in asthma." (PMID 36611927, 2022). "As we observed that SGK1 transcript levels were upregulated in individuals with asthma, this may alter the polarization of TH2 cells, leading to aberrant T2 signaling." (PMID 36611927, 2022). "Here, we observed that the gene SGK1 was upregulated in individuals with asthma." (PMID 36611927, 2022). "Indeed, upon performing qPCR analysis in additional subjects, we observed a significant increase in SGK1 transcript levels between asthma and healthy individuals." (PMID 36611927, 2022). "However, a larger validation cohort would be required to more definitively determine if increased SGK1 expression is specific to asthma or subgroupings of asthma." (PMID 36611927, 2022). "Furthermore, recent studies have identified dysregulated miRNAs in T cells from individuals with asthma, leading us to question whether miRNAs may regulate SGK1." (PMID 36611927, 2022). "However, it appears that the relationship of miR-19a and SGK1 is present in individuals both with and without asthma, suggesting a general mechanism during T cell polarization." (PMID 36611927, 2022).
B-cell lymphoma (5 papers, 2015 to 2025). "SGK1 was reported to be up-regulated in both AML, CML, and B-cell lymphoma, and has been shown to play a role in both chemotherapy resistance and radio-resistance due to its structural similarities to AKT24,25." (PMID 34349149, 2021). "There are no reports about SGK1 involvement in AML, but it has been described as mutated in B-cell lymphoma." (PMID 40613901, 2025).
endometrial cancer (5 papers, 2018 to 2025). Primary or metastatic malignant neoplasm involving the endometrium (mucous membrane that lines the endometrial cavity). "In the context of endometrial cancer, SI113 has been observed to markedly reduce the viability of endometrial cancer cells and to enhance apoptosis, while concomitantly activating endoplasmic reticulum stress by means of SGK1 inhibition." (PMID 40427579, 2025). "In endometrial cancer, VPS9D1-AS1 promotes tumor progression by acting as a molecular sponge for miR-377-3p, thereby upregulating SGK1 expression and enhancing cell proliferation, invasion, and EMT." (PMID 40443971, 2025). "It is noteworthy that ORAI1/STIM1 is upregulated by the serum and glucocorticoid inducible kinase (SGK1) and TGF-β in endometrial cancer cells, but downregulated by the AMP activated kinase (AMPK)." (PMID 29230527, 2018).
fibrosis (5 papers, 2013 to 2023). the formation of excess fibrous connective tissue in an organ or tissue in a reparative or reactive process. "Cardiac fibrosis was evaluated one month after myocardial ischemia in SGK1-/- and WT mice by histochemical analysis and collagen3a (Col3a) gene expression." (PMID 24265802, 2013).
metabolic syndrome (5 papers, 2013 to 2025). A cluster of metabolic risk factors for CARDIOVASCULAR DISEASES and TYPE 2 DIABETES MELLITUS. "In addition, IR can cause downregulation of SGK-1 expression, which promotes adipocyte and immune cell dysfunction, resulting in dyslipidemia and abnormal systemic inflammation, and finally accelerate atherosclerosis." (PMID 39309107, 2024).
Miscarriage (5 papers, 2015 to 2023). A pregnancy that ends at a stage in which the fetus is incapable of surviving on its own, defined as the spontaneous loss of a fetus before the 22th week of pregnancy. "Expression of SGK-1 has also been confirmed at both the molecular and protein level in decidua with decreased SGK-1 expression being associated with miscarriage." (PMID 28094006, 2017). "Fisher and Giudice revealed that in pregnant Sgk1 knockout (sgk1–/–) mice, the uteri/implantation sites, showed evidence of uterine bleeding, deficiency in fetal growth and spontaneous (30%) fetal loss akin to human miscarriage." (PMID 37280474, 2023). "In addition, animal experiments have also shown that blocking the gene expression of SGK1 in mice to reduce SGK1 levels can lead to miscarriage." (PMID 37280474, 2023). "Decreased SGK1 reduces the expression and activation of ENaC at the maternal–fetal interface, which mediates Na + currents involved in cell migration and proliferation, thereby affecting trophoblast invasion and proliferation, leading to miscarriage." (PMID 37280474, 2023). "In a previous study, we found that E2 could induce SGK1 expression and promote its phosphorylation in DSCs from early miscarriage." (PMID 37226177, 2023). "Importantly, a decrease in uterine Akt expression has been shown to result in abnormal decidualization in mice, and reduced SGK1 expression in DSCs has been observed in recurrent spontaneous miscarriage (RSM) patients." (PMID 26013399, 2015). "Our study found that SGK1 and its signaling pathway-related proteins (p-Nedd4-2, 14–3-3 protein, ENaC-α), estrogen and progesterone and their receptors (E2, P, ERβ, PR), and decidualization markers (PRL, PRLR, IGFBP-1) were expressed at lower levels in unexplained recurrent miscarriage tissue." (PMID 37280474, 2023).
pulmonary hypertension (5 papers, 2019 to 2025). Increased pressure within the pulmonary circulation due to lung or heart disorder. "In a model of hypoxia-induced pulmonary arterial hypertension, SGK1 activity was shown to be associated with hypoxic pulmonary macrophage infiltration, whereby knockout of SGK1 reduced macrophage content." (PMID 35998035, 2022). "Our results indicate that deficiency of SGK1 attenuates hypoxia-induced pulmonary hypertension." (PMID 31815093, 2019). "In our study, we found SGK1 induced in hypoxia-induced pulmonary hypertension and SGK1 deletion in mice inhibited the development of pulmonary hypertension." (PMID 31815093, 2019). "Therefore, SGK1 was suggested as a possible target for the treatment of pulmonary hypertension." (PMID 37336980, 2023). "Despite the wide tissue distribution of SGK1 and its sensitivity to various stimuli, its role in hypoxia-induced pulmonary hypertension was not fully defined." (PMID 31815093, 2019). "While global Sgk1 knockout mice do not display significant phenotypic changes under normal conditions, they have been shown to exhibit specific physiological alterations, such as reduced sensitivity to hypoxia-induced pulmonary arterial hypertension and impaired sodium retention on a low-salt diet." (PMID 40741328, 2025).
Ventricular arrhythmia (5 papers, 2017 to 2023). "Therefore, ventricular arrhythmias can be reduced by abolishing elevated SGK1 in the presence of pathogenic causes." (PMID 34823510, 2021). "These experiments provide clinical relevance of SGK1 as a target for treatment of ventricular arrhythmias in conditions with abnormal increases in sodium flux." (PMID 28336914, 2017). "We had previously shown that transgenic mice with chronic activation of SGK1 in the heart had an increased propensity to ventricular arrhythmias, and that this was likely due to a marked alteration in INa4." (PMID 28336914, 2017). "In conclusion, in this study, using CADD-based small molecule inhibitors of SGK1 as pharmacological probes to complement genetic inhibition of SGK1, we have demonstrated ‘proof-of-concept’ SGK1 inhibition as a therapeutic target for ventricular arrhythmias." (PMID 28336914, 2017). "Moreover, SGK1 has recently identified as a beneficial target for management of ventricular arrhythmia." (PMID 34823510, 2021). "As a prelude to determining the effectiveness of SGK1 inhibition to treat ventricular arrhythmias, we first tested the hypothesis that SGK1 directly regulates the cardiac voltage-gated sodium channel (Nav 1.5) activity in a heterologous expression system." (PMID 28336914, 2017).
amyotrophic lateral sclerosis (4 papers, 2011 to 2024). Amyotrophic lateral sclerosis (ALS) is a neurodegenerative disease characterized by progressive muscular paralysis reflecting degeneration of motor neurons in the primary motor cortex, corticospinal tracts, brainstem and spinal cord. "Various evidence in noncancerous mouse mammary cell lines, as well as in the transgenic model of amyotrophic lateral sclerosis (ALS), suggest a role for SGK1 in mediating cell survival in response to oxidative stress." (PMID 26908461, 2016).
atrial fibrillation (4 papers, 2023 to 2025). A disorder characterized by an electrocardiographic finding of a supraventricular arrhythmia characterized by the replacement of consistent P waves by rapid oscillations or fibrillatory waves that vary in size, shape and timing and are accompanied by an irregular ventricular response. "In this study, we found that SGK1, as a direct upstream regulator of ENaC, reflects the increased inflammatory response and sodium hydrate metabolism disorder in mice with acute onset of atrial fibrillation." (PMID 36899056, 2023). "In conclusion, the TNFSF14/LIGHT–PI3Kγ–SGK1 axis is not only an important mediator of the transition from chronic inflammation to fibrosis in the heart, but also provides a potential therapeutic target for atrial remodeling during the progression of atrial fibrillation." (PMID 41561130, 2025). "Additionally, the LIGHT-mediated PI3Kγ–SGK1 pathway may maintain the inflammatory microenvironment during the sustained phase of atrial fibrillation by inducing the expression of fibrotic factors such as TGF-β1, thereby further stabilizing the structural remodeling state of the atria." (PMID 41561130, 2025). "In the pathological process of atrial fibrillation, LIGHT activates SGK1 through a PI3Kγ-dependent pathway." (PMID 41561130, 2025).
chronic kidney disease (4 papers, 2020 to 2025). Impairment of the renal function secondary to chronic kidney damage persisting for three or more months. "Synthesis of the data from previous studies reveals that, in cases of senile osteoporosis, diabetic osteoporosis, and chronic kidney disease—mineral and bone disorder, SGK1 demonstrates elevated expression levels and abnormal activation." (PMID 40427579, 2025). "Impairment of renal phosphate elimination in chronic kidney disease (CKD) leads to enhanced plasma and tissue phosphate concentration, which in turn up-regulates transcription factor NFAT5 and serum & glucocorticoid-inducible kinase SGK1." (PMID 32015442, 2020).
Cognitive impairment (4 papers, 2022 to 2026). Abnormal cognition is characterized by deficits in thinking, reasoning, or remembering. "Therefore, a close link between sleep deprivation and advancing brain aging may be described by dysregulated SGK1 expression that leads to an increased risk of cognitive deficits." (PMID 35884632, 2022). "Elucidating the upstream and downstream targets of SGK1 and the related signaling pathways may help to understand the molecular mechanism of cognitive impairment and provide new therapeutic targets for PTSD." (PMID 39737082, 2024). "Thus, in this pathway, it can be hypothesized that when SGK1 is blocked, Rab4 also loses its role, thus exacerbating cognitive impairment." (PMID 39737082, 2024). "Similarly, virus-mediated down-regulation of SGK1 in the medial PFC (mPFC) of rats revealed that reduction of SGK1 expression in the mPFC decreases resistance to stressful memory deficits, suggesting that SGK1 is a key molecular and cellular mediator of cognitive impairment." (PMID 39737082, 2024).
endothelial dysfunction (4 papers, 2020 to 2025). In vascular diseases, endothelial dysfunction is a systemic pathological state of the endothelium (the inner lining of blood vessels) and can be broadly defined as an imbalance between vasodilating and vasoconstricting substances produced by (or acting on) the endothelium. "This fits well with a previous study proving the relevance of serum- and glucocorticoid-regulated kinase 1 (SGK1) for Th17 promotion during Ang-II-induced endothelial dysfunction and renal injury, since SGK1 itself is a Hippo pathway target gene." (PMID 40076765, 2025). "We demonstrate that in SS rats BMP4 plays a crucial role in HS-induced ENaC activity and endothelial dysfunction via p38 MAPK-dependent activation of Sgk1/Nedd4-2." (PMID 33194000, 2020).